STAT3 (signal transducer and activator of transcription 3)
Diseases named in the same sentence as STAT3 in open-access papers (continued):
Sharing a sentence is not in itself a finding about the gene and the disease.
tumor (continued). "Additionally, STAT3 induces tumor angiogenesis via elevating VEGFA levels in various tumors." (PMID 37752569, 2023). "However, it has been shown that STAT3 activity may also exert limiting effects on colonic carcinoma development in murine models, as well as suppress tumor cell invasiveness." (PMID 36982677, 2023). "However, even unphosphorylated STAT3 may promote tumor cell migration by interacting with the microtubule destabilizing protein—stathmin." (PMID 38067351, 2023). "Suspended in the peritoneal cavity, tumor cells face different challenges, like anoikis, which can be prevented by cell cluster (spheroid) formation, maintenance of mesenchymal and stemness state (e.g. via STAT3 signaling) and/or survival signaling like PI3K, MEK–ERK, or TNF–TNFR2–NF-κB3,12." (PMID 37095087, 2023). "Besides, STAT3 has immunosuppressive effects in the tumour microenvironment where its activation leads to inhibition of neutrophil, natural killer cell and effector T cell function, reduced DC maturation and expansion of Treg and myeloid derived suppressor cells." (PMID 37173424, 2023). "Inhibiting the STAT3 pathway might have therapeutic potential in ovarian cancer, as this pathway plays a pivotal role in the migration, invasiveness, and proliferation of tumor cells." (PMID 37514090, 2023). "Additionally, this study demonstrated that YAP/STAT3 signaling axis could promote tumor angiogenesis." (PMID 37329188, 2023). "It has been postulated that HLA-G may interact with unknown protein partners in tumor cells to activate the STAT3 pathway, but this study actually identifies a contemporary HLA-G binding partner with respect to its activation of the STAT3 pathway." (PMID 36780531, 2023). "Notably, WCP could inhibit the proliferation of H22 tumors not only by improving immune function, but also by promoting the apoptosis of tumor cells, likely through the IL-10/STAT3/Bcl2 and Cyto-c/Caspase8/3 signaling pathways, in H22 tumor-bearing mice." (PMID 37110586, 2023). "Furthermore, studies performed on NSCLC in A549 cells showed that the miR-206 antagomir therapy decreased tumor volume and the formation of intra-tumoral capillary tubes, and increased apoptosis by blocking the 14-3-3zeta/STAT3/HIF-1alpha/VEGF signaling pathway." (PMID 37569812, 2023). "Moreover, IL-6/JAK/STAT3 inhibits the anti-tumour immune response." (PMID 37753372, 2023). "Moreover, Cur could repolarize TAMs from pro‐tumor M2 to anti‐tumor M1 phenotype via inhibiting STAT3 activity." (PMID 36794651, 2023). "In addition, HMGA2, a tumour derivative, could up‐regulate the gene transcription of CCL2 in tumour‐associated macrophages (TAMs) by regulating the STAT3 signalling pathway." (PMID 36872292, 2023). "Overall, these data suggested that macrophage CD146 expression was controlled at least partially by TCM-induced STAT3 signaling and confirmed that CD146+ macrophages were reshaped in the TME, suggesting that the loss of CD146 expression in macrophages affected their role in tumor development." (PMID 37308559, 2023). "In this study, the authors discovered that sorafenib’s anti-tumor effects were increased in a mouse model of HCC by targeting the IL-6/JAK2/STAT3 signaling pathway with an IL-6 neutralizing antibody, implying that IL-6 may contribute to HCC patients’ resistance to sorafenib therapy." (PMID 37892997, 2023). "Galectin-4 was proposed as a tumor suppressor inhibiting cell proliferation by down-regulating wingless/integrated (Wnt) and IL-6/NF-κB/Signal transducer and activator of transcription 3 (STAT3) signaling that balance epithelial cell homeostasis in the intestine." (PMID 36873388, 2023).
tumor (continued). "PRMT1 could accelerate tumor progression and metastasis via STAT3 signaling pathway in HCC." (PMID 37725627, 2023). "Moreover, Quercetin could remarkably reduce the CYP3A and p-Stat3 expression pattern in the tumor tissues." (PMID 37710176, 2023). "Signal transducer and activator of transcription-3 (STAT3) was identified as a critical mediator of the oncogenic effects of CAFs and was a key transcription factor regulating the function of CAFs while crosstalking with tumour cells and immune cells within the TME." (PMID 38173726, 2023). "Therefore, STAT3 inhibitors affect polarization of TAMs in tumor therapy." (PMID 36739406, 2023). "Thus, interaction between BRG1 and the STAT3 pathway may be part of the mechanism by which BRG1 increases GBM tumour aggressiveness." (PMID 37433987, 2023). "Moreover, the expression of the tumor suppressor gene Latexin (LXN) was restored after STAT3 silencing, which might be related to observed tumor regression." (PMID 38067351, 2023). "Furthermore, tumor-associated macrophages exert an immunosuppressive effect by producing the chemokines and NF-κB p65/STAT3, which preferentially recruit non-cytotoxic T cell subsets." (PMID 36831441, 2023). "Importantly, inhibition of STAT3 signaling significantly attenuated MB tumor growth in subcutaneous and intracranial orthotopic xenografts, increased the sensitivity of MB tumors to cisplatin, and improved the survival of mice bearing high-risk MYC-amplified tumors." (PMID 37190167, 2023). "Inhibition of IL-6/JAK/STAT3 signaling can also affect the tumor microenvironment and has implications for antitumor immunity; therefore, determining whether co-targeting of immune checkpoints and the IL-6/JAK/STAT3 signaling pathway mightbe beneficial is important." (PMID 37720284, 2023). "Another subset of astrocytes characterized by high expression levels of the immune checkpoint PD-L1 and activation of the immunomodulatory factor STAT3 was identified in the peritumoral area, where they may potentially act as a barrier against anti-tumor T lymphocytes." (PMID 37020242, 2023). "However, our study reveals a critical role for the IL-6/STAT3/miR-214 axis during tumor progression which could be useful in clinical interventions." (PMID 36639824, 2023). "However, one should be aware that silencing STAT3 activity could also alter the functions of non-tumor cells within the TME." (PMID 38067351, 2023). "In addition, adenosine monophosphate-activated protein kinase (AMPK)/mammalian target of Rapamycin (mTOR) 48 and signal transducer and activator of transcription 3 (STAT3) 49 signaling pathways have also been reported to mediate the regulation of FASN in tumor proliferation and metastasis." (PMID 37497413, 2023). "Mechanistically, tumor cell-derived granulocyte-macrophage colony stimulating factor (GM-CSF) increased the expression of FcγRIIB on hematopoietic progenitor cells (HPCs) by activating specificity protein 1 (Sp1), subsequently FcγRIIB promoted the generation of MDSCs from HPCs via Stat3 signaling." (PMID 34976216, 2022). "Taken together, our findings suggest that mitochondrial hypofission induced by Drp1 might strengthen the invasion and proliferation of GHPA tumor cells by activating STAT3, providing us with a new perspective on how mitochondria regulate the development of IGHPAs." (PMID 35463323, 2022). "Therefore, inhibition of the STAT3 signaling pathway by increasing ROS levels in tumor cells may be a new target for anti-tumor drugs." (PMID 36371217, 2022). "Therefore, STAT3 may be a key target of reactive oxygen species in regulating tumor invasion and metastasis." (PMID 35911143, 2022). "In addition, our expression analyses showed that, among potential Mir34a targets, genes associated with the induction of STAT3, JUN and SRF expression signatures are presumably involved in the opposing regulation of intestinal homeostasis and tumor formation by Mir34a and Csf1r signaling." (PMID 36147476, 2022).
tumor (continued). "Moreover, CYTL1 might serve as a tumor suppressor with broad inhibitory effects on tumor metastasis and the phosphorylation of STAT3 in multiple tumor models." (PMID 36276067, 2022). "As the formation of phospho-STAT3 (Tyr705) requires chronic cytokine stimulation from neighboring stromal or inflammatory cells, the different in vitro and in vivo expression patterns of phospho-STAT3 (Tyr705) may result from different tumor microenvironments." (PMID 35836213, 2022). "Thus, IL-6/JAK/STAT3 may directly inhibit tumor cell growth or indirectly enhance the antitumor immune response effects of immune checkpoint inhibitors." (PMID 35799780, 2022). "Similarly, STAT1 activation may induce antiproliferative and proapoptotic responses and enhance antitumor immunity during carcinogenesis, while STAT3 activation enhances tumor cell survival/proliferation, motility, and immune tolerance." (PMID 36059536, 2022). "Moreover, targeting NK cell-intrinsic STAT3 could unleash their anti-tumor responses in some tumor models, while the consequences on other aspects of NK-cell functionality are difficult to predict." (PMID 35865518, 2022). "The rationale for combining BBI608 with checkpoint inhibitors was based on the hypothesis that inhibition of cancer stem cells and STAT3, a mechanism of tumor evasion from immune surveillance and resistance to immunotherapy, would overcome tumor resistance to immunotherapy." (PMID 35267638, 2022). "The ratio of CD4+/CD8+ T cells and the levels of their characteristically secreted cytokines, IFN-γ and IL-2, were induced to decrease by the tumor cells, while these immunosuppressive issues could be reversed via inhibiting the activation of STAT3 pathway by rosmarinic acid." (PMID 36615387, 2022). "Elevated levels of STAT3 is observed in tumor‐infiltrating immune cells and plays negative regulatory effects on neutrophils, natural killer (NK) cells, effector T cells, and DCs, indicating that STAT3 activation in immune cells likely leads to the down‐modulation of antitumor immunity." (PMID 36176733, 2022). "Our findings help in the elucidation of the molecular mechanism by which dysregulated mTORC1 signaling drives tumor angiogenesis, indicating that the components in the STAT3/miR-130b-3p/MBNL1 loop signaling pathway may be targeted for the treatment of mTORC1-related tumors." (PMID 36217202, 2022). "In addition to PD-L1, EVs transported to Mφs can promote the expression of cytokines IL-6, IL-10, and MCP-1 by activating the Janus kinase 2-signal transducer and activator of transcription 3 (JAK2/STAT3) pathway, leading to immunosuppression of Mφs and promotion of tumor development." (PMID 36032078, 2022). "However, the constitutive activation of STAT3 is Involved in many cellular processes, including survival, proliferation, invasion, angiogenesis, metastasis, and immunosuppression, all of which favor tumor initiation and progression." (PMID 36559280, 2022). "In turn, MC-C tumor exhibited low constitutive expression of phosphorylated STAT3 (pSTAT3) – an activated molecule that is involved in the transcription of genes that induce tolerogenic and immunosuppressive signals; – and low expression of surface PD-L1 in tumor cells and tumor infiltrating cells." (PMID 35922755, 2022). "Similar frequencies of JAK1, JAK2, and STAT3 genotypes were seen in patients stratified by age, phototype, nevi presence, sun exposure, sunburn episodes, type of sun exposure, tumor location, ulceration, type of growth, Clark level, Breslow thickness, clinical stage, and metastases." (PMID 35982955, 2022). "Growing evidence indicates that innate and adaptive immune cells could release inflammatory mediators such as cytokines, chemokines, growth factors and proteolytic enzymes, as well as activate transcription factors (NF-κB, STAT3, etc.), contributing to tumor progression when present in the TME." (PMID 36293016, 2022).
tumor (continued). "Moreover, betulinic acid reduced the levels of p-STAT3 in tumor tissues derived from KB cells." (PMID 36615262, 2022). "Furthermore, when comparing HCC tissue samples by median of nuclear STAT3 expression, CD3-, CD4-, CD8-, and FOXP3-positive immune cell counts were significantly higher in tumor tissues with high nuclear STAT3 expression compared to tumor tissues with low nuclear STAT3 expression of the tumor cells." (PMID 35267462, 2022). "Importantly, a reduced STAT3 activity augments the antitumor effects of sunitinib, whereas the constitutive activation of a STAT3 mutant rescues tumor cell death, suggesting that STAT3 activation is a crucial downstream mediator that executes sunitinib’s effects." (PMID 35562668, 2022). "Thus, the activation of STAT3 reversed miR-577-mediated anti-tumor effects in NSCLC." (PMID 35475457, 2022). "Furthermore STAT3 is responsible for providing the tumor cells with the energetic demands." (PMID 36374927, 2022). "Therefore, the reduction in STAT3 by SA14 overexpression may also alleviate MSH in tumour cells and reduce the accumulation of neoantigens, which might blunt the antitumour effect of anti‐PD‐L1 immunotherapy." (PMID 35858011, 2022). "Therefore, the levels of STAT3 and phospho-STAT3 in tumor were examined by western blot assay." (PMID 34875483, 2022). "Many studies have demonstrated that the altered STAT3 expression is accompanied by the abnormal autophagy activity, and they may promote or inhibit the occurrence and development of tumors in a synergistic or antagonistic manner in different tumor stages." (PMID 35559037, 2022). "Therefore, suppression of the JAK2/STAT3 pathway could shed new light on cancer treatment and afford new targets for tumor therapy." (PMID 36104717, 2022). "Moreover, the existence of a subpopulation of cells in tumors called cancer stem cells (CSCs) or tumor initiating cells (TICs), responsible for drug resistance, tumor metastasis, and relapse, is also reported to correlate with increasing levels of STAT3 activation." (PMID 36559280, 2022). "Moreover, JAK2/STAT3 is also involved in tumor genesis and development." (PMID 35216134, 2022). "Therefore, downregulating the expression of STAT3 indirectly via miR-106/20b could serve as a potential new therapeutic method to promote DC maturation and attenuate tumour stem cell proliferation." (PMID 36157880, 2022). "Therefore, the formation of tumor spheroids and STAT3 signaling activation may be a general phenomenon in polymer X-based cell cultures." (PMID 36359204, 2022). "As such, the improved chemosensitivity associated with NLR attenuation in our preclinical models suggest that combining chemotherapy with therapeutic strategies to mitigate neutrophil-stromal-tumor cell IL-1β/IL-6/STAT-3 signaling in PDAC patients may be advantageous." (PMID 36107485, 2022). "However, under certain circumstances, STAT3 can act as a tumor suppressor in various tumors." (PMID 36557902, 2022). "TAMs can interpret tumor cells directly and lead to chemoresistance through the production of colony-stimulating factors (CSF)-1, increasing protease activity, inducing stemness of cancer cells through IL-6-mediated activation of STAT3 signals, and inducing enzymes involved in drug inactivation." (PMID 35658848, 2022). "Interestingly, one study reported that WMP attenuated CAC by regulating the balance between “tumor-promoting bacteria” and “tumor-suppressing bacteria” and the NF-κB/IL-6/STAT3 pathway in mice, highlighting that WMP was a potential effective chemo-preventive drug." (PMID 35927991, 2022).
tumor (continued). "Therefore, the inhibition and regulation of IL-6/JAK2/STAT3 signaling pathway is conducive to the prevention and treatment of tumors and the improvement of prognosis, and it is also one of the important targets for screening anti-tumor drugs." (PMID 36591515, 2022). "Therefore, blocking the abnormal activity of STAT3 in tumor cells may potentially be used as a novel approach to intervene and treat tumors." (PMID 35942374, 2022). "STAT3 signaling in CAFs and tumor cells may induce stromal remodeling of the TME characterized by fibrogenesis, a dysregulated organization of the ECM, and fibroblast contractility, which promote tumor cell motility, invasive activity, and resistance to chemical and immunological therapies." (PMID 36010693, 2022). "As a response, some soluble mediators such as IL-6 (interleukin- 6) could be selectively released from BMSCs as well, and in turn, enhancing the proliferation capacity of tumor cells by stimulating the STAT3 (signal transducer and activator of transcription 3) signaling pathway." (PMID 35255950, 2022). "Studies with polyphenol molecule resveratrol, which specifically inactivates STAT3, show that it inhibits the development of Bregs and TGFβexpression, resulting in restoration of anti-tumour immune response and control of inhibition of tumour growth by effector T cells." (PMID 35350071, 2022). "Among STAT family members, STAT3 is the most well-studied member; it is overexpressed in the majority of human cancers, and targeting STAT3 signaling has been recognized as a potential strategy for treating cancer owing to its roles in tumor formation, metastasis, and drug resistance." (PMID 35313878, 2022). "Thus, depending on the type of tumor or the context that dominates the induction of STAT3, the soluble cytokine or receptor to target might vary." (PMID 36443756, 2022). "Together, these studies suggest that although STAT3 is a well-known mediator for tumor progression in numerous malignancies, however, it could be used to design specific pharmacological inhibitors derived from different sources for future therapeutics against EC." (PMID 35401182, 2022). "Similarly, knockdown of IL6R in tumor cells suppressed both IL-6/JAK/STAT3 and TGFβ signaling, and suppressed EVsMMA-MRC5-induced EMT marker expression, drug resistance, and invasion and migration, suggesting that IL-6R activation functions upstream of TGFβ pathway signaling in this context." (PMID 36266345, 2022). "TAM can release cytokines, especially IL6, which could bind specific receptors on CRC cell surface, activating JAK2/STAT3 signaling pathway, downregulating tumor suppressor miR-506-3p, and relieve the inhibition of the latter on FOXQ1 that results in enhanced invasion and metastasis of CRC." (PMID 35186730, 2022). "Finally, STAT3 contributes to the tumor-promoting inflammatory environment." (PMID 36139106, 2022). "Thus, targeting tumor acidosis may be a viable therapeutic strategy to prevent immune exhaustion, by inhibiting the increased expression of PD-L1 via STAT3." (PMID 35927628, 2022). "And then they found that gracillin exerts a powerful anti-tumor effect mainly by inhibiting the production of bioenergy mediated by glycolysis and oxidative phosphorylation in tumor cells.Yang found that Gracillin exhibits a powerful anti-colorectal cancer effect by inhibiting the STAT3 pathway." (PMID 35392243, 2022). "Moreover, the elevated lactate in TME can promote the polarization of tumor-related macrophages (TAMs) to M2 by activating the ERK/STAT3 signaling pathway, and tumor cells tend to survive and metastasize through its secretion of anti-inflammatory and promoting angiogenesis cytokines." (PMID 35280985, 2022). "Finally, STAT3 has been shown to block the expression of inflammatory factors during tumor growth." (PMID 36080130, 2022).